YWHAZP2 (tyrosine 3-monooxygenase/tryptophan 5-monooxygenase activation protein zeta pseudogene 2)
Gene: Processed pseudogene on chromosome 2 (126,557,435 to 126,558,162, reverse strand). Ensembl gene ENSG00000213236.
Diseases named in the same sentence as YWHAZP2 in open-access papers:
YWHAZP2 is named in the same sentence as 4 diseases in open-access papers, as found by Europe PMC text mining. Sharing a sentence is not in itself a finding about the gene and the disease. The quoted sentences say what the papers report.
juvenile idiopathic arthritis (1 paper, 2024). Juvenile idiopathic arthritis (JIA) is the term used to describe a group of inflammatory articular disorders of unknown cause that begin before the age of 16 and last over 6 weeks. "Additionally, YWHAZP2, YWHAZP3, and YWHAZP10 expression is elevated in a study of LPS-treated PBMC of juvenile idiopathic arthritis patients." (PMID 38674334, 2024).
psoriatic arthritis (1 paper, 2024). Joint inflammation associated with psoriasis. "A study of T cells from the blood and synovial fluid of psoriatic arthritis patients revealed the expression of YWHAZP3 and YWHAZP10 in both leukocytes and T cells; the expression of YWHAZP1, YWHAZP5, and YWHAZP6 in leukocytes only; the expression of YWHAZP2 in T Cells only." (PMID 38674334, 2024).
YWHAZP2 also shares sentences with these, for which no sentence is quoted: autoimmune thrombocytopenia (1 paper); rheumatoid arthritis (1).